CRP (C-reactive protein)
Diseases named in the same sentence as CRP in open-access papers (continued):
Sharing a sentence is not in itself a finding about the gene and the disease.
anemia (continued). "We therefore ran the analyses in women without inflammatory response (CRP < 5), and found only minor changes in the mean/median concentration and prevalence rates of ID and anaemia across ethnic groups and conclude that inflammation could not explain the differences observed in our population." (PMID 35754987, 2022). "Low C-reactive protein (CRP), blood leucocytes (LPK), and carcinoembryonic antigen (CEA) were associated with CR rates in the scRT+CT group but not in any of the other groups, whereas anemia did not significantly associate with CR rate in any of the treatment groups in univariate analyses." (PMID 33375133, 2020). "Furthermore, over time, neither the mean corpuscular hemoglobin (MCH) and C-reactive protein (CRP) levels, as markers of infection-associated anemia or systemic inflammation, respectively, nor the monocyte/lymphocyte ratio, showed any difference between the two species." (PMID 31736945, 2019). "Our study found that AS with anemia had significantly higher BASDAI, ASDAS indices, CRP, and ESR compared to non-anemic patients, indicating a close correlation between disease activity, inflammation, and anemia." (PMID 39908327, 2025). "Laboratory investigations showed hypoxemia, but no anemia, and normal white blood cell (WBC), CRP, and PCT levels." (PMID 40918668, 2025). "Specifically, the investigators considered milder systemic symptoms the consequence of a failure to increase IL-6 levels (with the result of normal baseline values of CRP and ESR, and an absence of anemia)." (PMID 40508840, 2025). "The analysis revealed moderate anaemia, a low eosinophile count (3/mmc), no other hematologic changes and inflammatory syndrome (VSH = 87/mm3, CRP = 2.45 mg/dL)." (PMID 40126322, 2025). "Initial laboratory investigations showed anemia, elevated ESR and CRP, while autoimmune and infectious screens were negative." (PMID 41221362, 2025). "Laboratory results revealed a moderate non-regenerative anaemia, marked monocytosis, mildly increased ALP, mild-to-moderate hypercholesterolemia, mild hypouremia, and elevated CRP levels." (PMID 41012738, 2025). "Significant positive correlations were observed between OPG and ferritin, sTfR, sRANKL, CRP, IL-6, RF, and DAS28, and a negative correlation was found with serum iron in the ACD subgroup but not in the combined anemia ACD/IDA subgroup." (PMID 39684440, 2024). "sRANKL was positively correlated not only with sRAGE but with prohepcidin, CRP, IL-6, RF, anti-CCP antibodies, and DAS28 in the ACD subgroup but not in the subgroup with combined anemia (ACD/IDA)." (PMID 39684440, 2024). "Laboratory evaluations can show anemia, elevated liver function tests (LFTs), inflammatory markers (ESR and CRP), and negative levels of ANA, P‐ANCA, and C‐ANCA, as seen in our patient." (PMID 39588247, 2024). "There were significant positive correlations between sRAGE and CRP, RF, and anti-CCP antibodies in the subgroup without anemia (with normal Hb level) and with IL-6 in the subgroup with anemia (with low Hb level)." (PMID 39684440, 2024). "Our study showed a negative correlation between Hb concentrations and CRP and ESR in children with TB-related anemia." (PMID 38886797, 2024). "For other cases, a full blood count, C-reactive protein (CRP), and fecal calprotectin levels should be tested to rule out anemia or inflammation." (PMID 38496157, 2024). "Compared to patients without SCVs, patients with isolated SCVs had heightened CRP, ESR, and PCT levels and were more likely to have a higher WBC count and NEUT%, and the proportion of patients with anaemia was more than half." (PMID 38259974, 2023). "Both UC and CD patients showed a negative correlation between CRP concentration and HGB, which is consistent with the clinical assessment of the study group and the frequent occurrence of anaemia in severe forms of IBD." (PMID 37048531, 2023).
anemia (continued). "Subjects with anemia had higher EPO, iFGF23, CRP, and phosphate and lower eGFR, while we were not able to show statistical difference regarding PTH, D vitamin, and calcium levels." (PMID 35739404, 2022). "Therefore, the notion of significantly elevated CRP levels in the non-prior rhGH group may not only explain the higher frequency of anemia as a consequence of inflammation but also subclinical graft rejection in these patients which may contribute to the inferior long-term graft function." (PMID 34542703, 2022). "Blood examination on the day of fever revealed high white blood cell (WBC) count (20,400/μL), C-reactive protein (CRP) (1.79 mg/dL), and amyloid A protein (169 mg/dL) without anemia." (PMID 35739566, 2022). "Plateletcrit was higher in women with anemia, whereas none of the other indicators of inflammation (WBC, CRP, and cytokines) or infections or infant anthropometry differed between anemic and non-anemic women." (PMID 36079755, 2022). "No obvious abnormalities related to hepato-renal damage or anemia due to systemic administration in all hDPSC-treated CXMDJ were noted in blood tests, which included the determination of ALP, AST, BUN levels, and CRP levels." (PMID 33494794, 2021). "In the subsequent week of follow-up, there was no recurrence of his rash, his liver enzymes were not elevated, he had improving anemia with hemoglobin at 13.1 g/dL, and resolving inflammatory markers with ESR at 29 mm/hour and CRP within normal limits." (PMID 34955100, 2021). "CRP, hepcidin and AGP levels were unchanged in UEA as compared to participants without anemia (p > 0.05)." (PMID 34836070, 2021). "Levels of inflammatory markers (hepcidin, CRP, AGP and IL-6) were significantly higher in AI as compared to participants without anemia (p < 0.05), and IL-6 was higher in CKD; IL-6 and CRP were also significantly higher in AMC." (PMID 34836070, 2021). "Complete blood count with biochemical parameters was performed as a follow-up to assess anemia and the state of AAV after steroid pulse therapy revealed a drastic drop in the patient’s platelet count to 47,000/μL without elevated levels of C-reactive protein." (PMID 34126959, 2021). "Noteworthy, TB patients who were anemic at pre-ATT exhibited increased values of ferritin, ESR, CRP and decreased levels of albumin, AST and ALT at day 60 than those who did not have anemia at the study enrollment." (PMID 30718725, 2019). "A meta-analysis of routine blood-tests in AECOPD found that anaemia, hypoalbuminemia and elevated levels of the cardiac biomarkers pro-BNP and troponin-T, but not high-sensitivity C-reactive protein (hs-CRP) predicted mortality from COPD." (PMID 29783959, 2018). "For example, among chronic kidney disease patients with anaemia, only inflammatory markers such as interleukin (IL)-6, IL-8 and tumour necrosis factor (TNF)-α were correlated with some of the HR-QoL domains, but CRP was not." (PMID 26474291, 2015). "In this study, the prevalence of elevated plasma CRP and AGP was low; indicating the presence of ongoing or recent acute inflammation in the study population was low, however that may not rule out some chronic infections but then their presence would have caused anemia rather than contrary." (PMID 23714325, 2013). "Laboratory examination revealed an elevated and rapidly increasing CRP (C-reactive protein), ESR (Erythrocyte sedimentation rate), leukocytosis with elevated neutrophils (no eosinophilia) with a limited normocytic anemia." (PMID 22991676, 2012). "Participants with anemia of chronic diseases had significantly higher IL-6 and C-reactive protein (CRP) levels, while those with unexplained anemia had significantly lower CRP than nonanemic controls." (PMID 23091709, 2012). "Preoperative anemia (OR 5.91, p = 0.026), higher ASA score (OR 1.77, p = 0.033), and surgical delay (OR 1.67, p = 0.024) independently predicted infection, while age and CRP showed non-significant trends." (PMID 41302186, 2025).
anemia (continued). "Notably, CRP and HGB demonstrated a strong negative correlation (−55%), supporting the well-established role of systemic inflammation in anemia of chronic disease." (PMID 41395368, 2025). "Nonspecific laboratory abnormalities in IgG4-RD may include anemia, increased ESR, and elevated CRP." (PMID 40562859, 2025). "He did not have any evidence of interstitial lung disease (ILD) nor myositis, while his blood showed anaemia with moderately elevated inflammatory markers (white blood cell (WBC) count 10.32 109/L of which 77% neutrophils, C-reactive protein (CRP) 14 mg/L) and were otherwise unremarkable." (PMID 39802335, 2025). "Pulmonary vessel involvement leads to chronic hypoxia and stimulates erythropoiesis, and is usually not observed in patients presenting with anemia, suggesting that our patient presented in the active stage, based on her elevated ESR and CRP levels, as well as CTA findings." (PMID 39600747, 2024). "The overall prevalence of inflammation (CRP > 5 mg/L), ID (age-related ferritin concentration < 12 μg/L and < 15 μg/L), IDA (concurrent ID and anaemia) and AI (concurrent anaemia and inflammation in the absence of ID) were respectively, 63.1%, 34.6%, 12.9% and 30.2%." (PMID 37507740, 2023). "This subject was a 69-year-old woman who had microcytic anemia (Hb 11.8 g/dL, mean corpuscular volume, MCV, 77.0 fL) with a TSAT level of 6.0%, a hepcidin level of 0.8 nM, a ferritin level of 24.0 μg/L, and no signs of inflammation (CRP 1.6 mg/L)." (PMID 35163840, 2022). "Using a linear regression analysis with fixed effects, we found that CRP level (p < 0.001), transfused RBC units (p < 0.001) and moderate anaemia (p = 0.04) were predictors for prolonged LOS but not gender, BMI, ID, iron supplementation, preoperative Hb increase, mild or severe anaemia." (PMID 35392839, 2022). "There were higher levels of WBC, CRP, ALT, and lactate and lower levels of albumin, PLT, and hemoglobin in the non-survivor group (all P < 0.001), indicating more severe inflammation, liver dysfunction, poor circulation, and anemia in the non-survivor group." (PMID 36210933, 2022). "It has been reported that anemia in CRC frequently shows a microcytic phenotype, especially in high-grade T stage, proximal colon tumor location, lymph node metastasis, and elevated serum CRP with or without hypoalbuminemia." (PMID 34221966, 2021). "Notably, patients suffering from anemia demonstrated significantly higher IL6 (p = 0.009) and CRP (p = 0.031) concentrations as compared to non-anemic patients." (PMID 33087116, 2020). "However, children with elevated CRP and/or AGP had higher levels of anemia compared to children with no inflammation (p < 0.05)." (PMID 31547543, 2019). "Additionally, all of the criteria to classify abnormal biochemistry (increased CRP or IL6, anemia and low serum albumin) were not available." (PMID 31118043, 2019). "A relatively large study involving 8,513 participants free of CAD found that, independent of anemia, raised RDW (>12.6%) predicted coronary artery disease (CAD) mortality up to 6 years after assessment, and was a better predictor of mortality than C-reactive protein levels (CRP)." (PMID 30212481, 2018). "It is noteworthy that although inflammation may play a role in the higher prevalence of anaemia amongst the HAART-naive individuals, WBC values were within normal reference limits and we measured CRP to rule out all participants who had active inflammation." (PMID 27092270, 2016).
depression (1,504 papers, 2006 to 2026). "The Spearman correlation and binary logistic regression analyses revealed the potential associations between depression and several factors, such as age, albumin, C-reactive protein, GNRI, and sarcopenia score (p < 0.05)." (PMID 41788681, 2026). "The OR for Ln CRP was 1.32, indicating that each unit increase in log‐transformed CRP levels was associated with a 32% higher likelihood of experiencing depression." (PMID 40851223, 2026). "The mediational E values for the average causal mediation effects on the risk ratio scale were 1.148 for depression, 1.025 for CRP, and 1.153 for CRP and depression together in the mediation models." (PMID 41243808, 2026). "First, we used cross-sectional and longitudinal non-genetic analysis to examine the association between circulating levels of CRP and depression/cognitive performance." (PMID 40348744, 2025). "CRP is recognized as a risk factor associated with various psychological and physical symptoms, including cognitive function, depression, cardiovascular disease, and irritable bowel syndrome (IBS)." (PMID 39858953, 2025). "Inflammatory cytokines are involved in the development of neuropsychiatric symptoms and depression and the risk factors associated with increased circulating inflammatory cytokines and CRP." (PMID 40966684, 2025). "previously elucidated the crucial role of CRP in mediating the association between trauma and depression, yet the potential mediating role of HMGB1 in this process remains inadequately explored." (PMID 40557138, 2025). "Elevated C-reactive protein (CRP) and soluble IL-6 receptor levels have been consistently associated with depression severity, particularly in patients with pre-existing vulnerability to affective disorders." (PMID 40649991, 2025). "The association between C-DII and depression was explainedby CRP (23.2%) and WC (20.9%) as mediator variables (indirect effect βcoefficient/total effect β coefficient)." (PMID 40110388, 2025). "The largest case study involving approximately 27,000 MDD patients from the UK Biobank demonstrated a significant association between elevated blood levels of CRP and depression." (PMID 41301474, 2025). "Elevated CRP levels are linked to conditions such as strokes, periodontitis, and depression, with an increased risk of brain atrophy and dementia." (PMID 40943152, 2025). "Positive associations between CRP and interleukin-6 (IL-6; a proinflammatory cytokine), and somatic depression symptoms have been observed in adults and children." (PMID 40823322, 2025). "Several studies investigating specific symptoms of depression have reported that inflammation indexed by C-reactive protein (CRP) was significantly associated with fatigue, sleep disturbances, and eating problems." (PMID 41239360, 2025). "DM and depression were all associated with higher CRP, while carrying APOE E4 was associated with lower CRP levels in both univariable and multivariable GLM (all p< 0.001) in all populations." (PMID 40778276, 2025). "In this context, weinvestigated the mediating role of BMI-z score, WC, and WHtR for the associationbetween dietary inflammation and depression, and CRP and HDL-c levels foranxiety." (PMID 40110388, 2025). "Elevated CRP levels are observed in over 29% of patients with depression and are associated with the severity and symptoms of major depressive disorder." (PMID 41018179, 2025). "This retrospective study identified preoperative anxiety, preoperative depression, preoperative pain, duration of tourniquet use, pain upon discharge, and postoperative C-reactive protein levels as independent risk factors of CPSP after TKA." (PMID 40103861, 2025). "Second, although CRP is commonly used to index overall inflammation, has been associated with depression, and is related to other inflammatory markers including IL-6, it is still a single inflammatory marker." (PMID 40357904, 2025).
depression (continued). "Large-scale research in adults, using UK Biobank data, observed a causal relationship between both inflammatory markers, CRP and IL-6, and depression." (PMID 40823322, 2025). "Background/Objectives: C-reactive protein (CRP) has been acknowledged to be associated with depression, loneliness, and stress, as well as physical health conditions." (PMID 40565981, 2025). "Participants who reported poor sleep quality demonstrated stronger associations between elevated CRP levels and increased symptoms of depression, anxiety, and chronic fatigue." (PMID 41333345, 2025). "Research shows that visceral fat accumulation is linked to elevated central inflammatory markers like C-reactive protein, with chronic low-grade inflammation being a key pathological mechanism in depression." (PMID 41162914, 2025). "C-reactive protein (CRP) is another important biomarker of inflammation that has been linked to depression." (PMID 40004109, 2025). "Meta-analyses have demonstrated that low-grade inflammation (CRP >1–3 mg/L) raises depression risk 1.5-fold." (PMID 40912718, 2025). "Elevated CRP levels, for instance, have been consistently associated with both major depressive disorder and an increased risk of myocardial infarction." (PMID 40218134, 2025). "Taken together, these observations implicate CRP‐mediated inhibition of dopaminergic neurotransmission in depression pathogenesis, with further investigation of the underlying mechanisms warranted." (PMID 41425661, 2025). "Late-onset depression was less responsive to antidepressant medication, and a poor antidepressant response rate was associated with a higher level of CRP in late-onset depression." (PMID 40955269, 2025). "Physiologically, chronic social isolation has been linked to dysregulation of the hypothalamic-pituitary-adrenal (HPA) axis and elevated inflammatory markers (e.g., IL-6, CRP), which are implicated in depression." (PMID 40462874, 2025). "A genome-wide association study revealed that genetic and epigenetic networks related to inflammation, such as polymorphisms in inflammatory mediators (CRP, tumor necrosis factor α, etc.), are closely associated with the severity of depression." (PMID 40365002, 2025). "Similar research using UK Biobank data found an association between CRP and anxiety, however this association was attenuated when controlling for depression and health-related factors." (PMID 40823322, 2025). "Prior studies have also identified associations between increased CRP levels and post-stroke depressive symptoms and prognosis, with CRP serving as a predictive marker for post-stroke depression." (PMID 41018179, 2025). "Markers of inflammation or immune activation (including TNFα, CRP, IL-6) are closely associated with depression and sleep quality." (PMID 40313235, 2025). "The analytical results demonstrated that AGP concentrations exhibited superior prognostic accuracy for depression compared to CRP, as a conventional risk predictor (AUC: 0.701 vs 0.578, P < 0.001)." (PMID 40530060, 2025). "In three ixekizumab trials in psoriasis, depression remitted in up to 45% of comorbid patients following IL-17A treatment, however mood improvement was only weakly associated with CRP reduction (r = 0.11, p < 0.001)." (PMID 39959848, 2025). "Higher levels of inflammatory markers, like interleukin-6 (IL-6) and C-reactive protein, are linked to depression." (PMID 40995176, 2025). "Our analysis identified preoperative anxiety and depression, preoperative pain, duration of tourniquet use, pain upon discharge, and one-day postoperative CRP levels as independent risk factors for CPSP in TKA patients." (PMID 40103861, 2025). "Larger initial increases in CRP were similarly associated with more improvement in neurovegetative symptoms of depression in those with relatively higher CRP at post-treatment but not in those with lower post-treatment CRP." (PMID 39834556, 2025).